NUDT6 (nudix hydrolase 6)
Description:
Mediates the hydrolysis of some nucleoside diphosphate derivatives, such as NADH and FAD (in vitro). May contribute to the regulation of cell proliferation.
Synonyms: FGF2AS; gfg-1; gfg; FGF-AS; ASFGF2; GFG1
Tractability: PROTAC: ubiquitination databases record sites on it.
Gene: Protein-coding gene on chromosome 4 (122,888,697 to 122,922,968, reverse strand). Ensembl gene ENSG00000170917.
Subcellular location: Mitochondrion (Isoform 1); Nucleus (Isoform 2); Cytoplasm
Gene Ontology:
Molecular function: FAD diphosphatase activity; NADH pyrophosphatase activity; hydrolase activity
Biological process: negative regulation of cell cycle; negative regulation of cell population proliferation
Cellular component: cytoplasm; mitochondrion; nucleus
Genetic constraint (gnomAD): Loss-of-function variants: 15 observed, 20.88 expected, observed/expected ratio (o/e) 0.72, 90% interval 0.48 to 1.11. The upper end of that interval is the gene's LOEUF score, 1.11, which puts it in group 4 of 6, group 1 being the genes least tolerant of losing a copy. Missense variants: 200 observed, 238.97 expected, observed/expected ratio (o/e) 0.84, 90% interval 0.75 to 0.94. Synonymous variants: 93 observed, 94.21 expected, observed/expected ratio (o/e) 0.99, 90% interval 0.83 to 1.17.
Homologues: Orthologues: chimpanzee NUDT6 (99% identical), macaque NUDT6 (95% identical), dog NUDT6 (82% identical), pig NUDT6 (80% identical), mouse Nudt6 (73% identical), rat Nudt6 (72% identical), tropical clawed frog nudt6 (60% identical), zebrafish nudt6 (54% identical), Drosophila melanogaster CG8128 (31% identical).
Diseases named in the same sentence as NUDT6 in open-access papers:
NUDT6 is named in the same sentence as 13 diseases in open-access papers, as found by Europe PMC text mining. Sharing a sentence is not in itself a finding about the gene and the disease. The quoted sentences say what the papers report.
esophageal adenocarcinoma (2 papers, 2012 to 2021). A malignant tumor with glandular differentiation arising predominantly from Barrett mucosa in the lower third of the esophagus. "It is reported that NUDT6 is abundantly expressed in esophageal adenocarcinoma and is associated with poor disease-free survival." (PMID 34150632, 2021).
abdominal aortic aneurysm (1 paper, 2025). Enlargement and ballooning of the vessel that supplies arterial blood to the abdomen, pelvis and legs. "Expression of nudix hydrolase 6 (NUDT6), an antisense transcript targeting fibroblast growth factor 2 (FGF2), increases in tissue samples from patients with abdominal aortic aneurysm and carotid artery disease." (PMID 40224357, 2025).
cerebrovascular diseases (1 paper, 2012). "The data presented here revealed novel angiogenesis-related genes, like Bai1 and Nudt6 that play roles in brain development and in this manner, expected to contribute to basic and clinical research on cerebrovascular diseases." (PMID 23020941, 2012).
colorectal cancer (1 paper, 2012). A primary or metastatic malignant neoplasm that affects the colon or rectum. "More recently, overexpression of recombinant NUDT6 in human colorectal cancer cells was reported to increase cell proliferation and colony formation in soft agar, raising the possibility that NUDT6 protein itself has proliferative and/or oncogenic activity." (PMID 24704982, 2012).
gastric tumor (1 paper, 2023). "Among autophagy genes in the Reactome database, PRMT1 was negatively correlated with genes such as ATG9A, DYNC1H1, EPAS1, PINK1, TSC1, TUBB6, and ULK1 in gastric tumor tissues (STAD-TCGA) and positively correlated with HMMR, ESCO2, CHAC2, and NUDT6 (STAD-TCGA)." (PMID 37564212, 2023).
glioma (1 paper, 2012). A benign or malignant brain and spinal cord tumor that arises from glial cells (astrocytes, oligodendrocytes, ependymal cells). "FGF2 and NUDT6 are co-expressed in rat C6 glioma cells, and ectopic overexpression of NUDT6 suppresses cellular FGF2 accumulation and cell cycle progression." (PMID 24704982, 2012). "In SEG-1 cells and C6 glioma cells NUDT6 over-expression reduced cellular FGF2 immunoreactivity and inhibited cell cycle progression and proliferation, whereas in rat GH3 pituitary adenoma cells NUDT6 inhibited cell cycle progression and proliferation, but did not suppress FGF2 levels." (PMID 24704982, 2012). "In the present report, we have used an siRNA-mediated gene knockdown approach to further elucidate the role of endogenous NUDT6 in the regulation of FGF2 expression and function in rat C6 glioma cells." (PMID 24704982, 2012).
tumor (4 papers, 2012 to 2023). "The expression and translation of FGF2 and NUDT6 are tightly linked, and show reciprocal patterns of expression in a variety of tissues during development, and in normal vs. tumor cells." (PMID 24704982, 2012). "ANGPTL4, LTB4R, CD72, and NUDT6 were downregulated, as their expression levels were higher in the healthy group and lower in the tumor group." (PMID 36911403, 2023). "We have previously demonstrated that constitutive or Tet-inducible over-expression of recombinant NUDT6 inhibits cell cycle progression and proliferation in rat and human tumor cells." (PMID 24704982, 2012).
NUDT6 also shares sentences with these, for which no sentence is quoted: cancer (2 papers); colitis (1); colon adenocarcinoma (1); Obesity (1); pituitary adenomas (1); sarcoma (1).